RN7SKP202 (RN7SK pseudogene 202)
Gene: Miscellaneous RNA gene on chromosome 10 (68,158,079 to 68,158,408, forward strand). Ensembl gene ENSG00000222371.
Homologues: Orthologues: chimpanzee 7SK (87% identical), mouse Gm54931 (57% identical). Paralogues in human: RN7SKP176 (71% identical), 7SK (71% identical), RN7SKP203 (71% identical), RN7SKP180 (70% identical), RN7SKP133 (70% identical), RN7SKP9 (69% identical), RN7SKP79 (69% identical), RN7SKP255 (69% identical), RN7SKP146 (68% identical), RN7SKP217 (68% identical), RN7SKP124 (68% identical), RN7SKP251 (68% identical), and 284 more.